S100A9 (S100 calcium binding protein A9)
Diseases named in the same sentence as S100A9 in open-access papers (continued):
Sharing a sentence is not in itself a finding about the gene and the disease.
COVID-19 (continued). "Transcriptomic analyses have shown overexpression of S100A8, S100A9, S100P and S100A12 in lung tissue from fatal COVID-19 patients." (PMID 41164170, 2025). "The expression of S100A9 and S100A8 proteins is increased in various pulmonary diseases, including idiopathic pulmonary fibrosis, COPD, COVID-19 and lung cancer." (PMID 39516272, 2025). "Interestingly, many pro-inflammatory genes including S100A8 and S100A9, chemotaxis genes such as CXCR2 and FPR1, and NETosis-associated genes such as TIMP1 were highly expressed in neutrophils of ANPEP-high patients with COVID-19 compared with ANPEP-low patients with COVID-19." (PMID 40168094, 2025). "Key biomarkers of COVID-19, such as CXCL8, S100A9, and HLA class I genes, have been identified as critical hub genes and the main players within these networks." (PMID 40580453, 2025). "In our study, we observed a significant upregulation of S100A9 and its heterodimer partner S100A8 in PLWH with COVID-19 compared to HCs." (PMID 40568587, 2025). "The gene expression of S100A9, GAPDH, and LY96 was increased in all data of severe COVID-19 patients." (PMID 38262689, 2024). "This work identified specific overexpressed genes related to neutrophils only in severe COVID-19 patients, such as SPI1, SLPI, S100A9, and BRI3, which indicates a specific expression regulation that occurs only in SARS-CoV-2 infection." (PMID 38262689, 2024). "Thirdly, genes involving in neutrophil-mediated immunopathology (e.g., S100A8, S100A9 and S100A12, etc.)and pro-inflammatory responses were elevated in COVID-19 acute necrotizing encephalopathy patients." (PMID 37848421, 2023). "We also observed that during severe COVID-19, S100A8 and S100A9 were considerably upregulated in multiple other cell types, such as B cells, granulocytes, PB, and DC." (PMID 37936693, 2023). "We found that the plasma levels of HP, LTA4H, S100A9, SAA1, SAA2, and SERPINA3 were significantly elevated in more severe COVID-19 conditions, exhibiting good clinical predictive value and promising applications." (PMID 37197655, 2023). "The plasma of severe COVID-19 patients is also characterized by highly elevated calprotectin, a heterodimer of S100A8 + S100A9 alarmins produced by neutrophils which can facilitate nitrosylation of GAPDH108." (PMID 37147288, 2023). "They found that S100A6, S100A9, and S100A12 were predictors of severe AP, and that a specific subtype of neutrophils was responsible for COVID-19-induced AP." (PMID 36830652, 2023). "Among the mRNAs up-regulated during COVID-19 (scRNA-seq data), S100A8 and S100A9 experienced the strongest derepression upon PIRAT knockout." (PMID 35998224, 2022). "Among them, S100A9, AHNAK, and CX3CR1 have been reported as potential COVID-19 biomarkers previously, and the others (TRAF3IP3 and LFNG) are closely associated with the immune and virus-related signaling pathways." (PMID 35885892, 2022). "This notion was further corroborated in qRT-PCR and FACS validations, which confirmed the control of S100A8, S100A9, ITGAX, and IRF5 by PIRAT and regulation of these factors during COVID-19." (PMID 35998224, 2022). "For example, S100A8, S100A9, and S100A12 levels in blood have recently been shown to correlate with disease severity in COVID-19 patients infected with SARS-CoV-250,51." (PMID 35396513, 2022). "Meanwhile, CXCL8, S100A8, S100A9, S100A12, FCGR1A, PADI4, and BCL2A1 showed significant increases in severe COVID-19 when compared with mild COVID-19 (p <0.05)." (PMID 36159873, 2022). "These proteins are up-regulated in the severe forms of COVID-19, and can induce inflammatory cytokines, influence lipid metabolism, and induce neutrophil activation, as shown for S100A8 and S100A9, thus possibly contributing to amplify the cytokine storm." (PMID 34876157, 2021).
COVID-19 (continued). "In contrary, some important cytokines in COVID-19 cytokine storm such as CXCL10, IL-6, CCL2, CCL20, IL-8 and S100A9 showed a trend of slightly lower levels in patients with asthma in all three COVID-19 severity groups." (PMID 34238349, 2021). "We found here that genes related to neutrophil activation, including S100A8, S100A9, and S100A12, were expressed at higher levels in monocytes from severe COVID-19 patients than those in mild cases." (PMID 33101705, 2020). "Increased expressions of S100A8, S100A9, and S100A12 calgranulins found in the BALF fluid from COVID-19 patients indicate their potential role in generating the proinflammatory response." (PMID 33335518, 2020). "In HSPCs of COVID-19, late-phase CD14+ monocytes retain elevated levels of inflammatory mediators such as S100A8 and S100A9 relative to both healthy controls and early-phase samples, underscoring their progression toward a more differentiated, pro-inflammatory phenotype." (PMID 41550933, 2025). "S100A9 mediates a variety of respiratory diseases, such as chronic obstructive pulmonary disorder (COPD) and infectious diseases, including tuberculosis, influenza and coronavirus disease 2019 (COVID-19) by forming a heterodimer with S100A8." (PMID 39516272, 2025). "Similarly, for CD14 and CD16 monocyte cells in severe COVID-19, CEBPD and FOS were particularly activated in the two cell types, and CEBPD upregulated S100A8 and S100A9." (PMID 37936693, 2023). "S100A9, AHNAK, and CX3CR1 have all been identified as relevant COVID-19 biomarkers." (PMID 35885892, 2022). "S1 cells exhibited the highest expressions of alarmins S100A8, S100A9, S100A12 and toll-like receptors TLR4 and TLR8, all of which are involved in neutrophil activation and were the most mature neutrophils in both KD and Severe COVID-19 patients." (PMID 36159873, 2022). "Finally, correlation between S100A6, S100B, S100A8, S100A9, S100A12, and S100P and COVID-19 pathogenesis is discussed." (PMID 35892571, 2022). "According to some studies, S100A4, S100A9, and S100A10 expression is proportional to neutrophil/lymphocyte ratio, and may reduce peripheral blood lymphocytes in COVID-19 patients." (PMID 35892571, 2022). "Additionally, neutrophils in COVID-19 express high S100A8 and S100A9, which serve as alarmins to amplify inflammation." (PMID 35401519, 2022). "In addition, a recent study demonstrated that S100A4, S100A9, and S100A10 have a role in the inflammatory conditions, as well as the severity, of COVID-19 patients, and have the ability to influence the prognosis of the severe form of the disease." (PMID 35892571, 2022). "Among them, S100A9, AHNAK, and CX3CR1 have been reported to be important biomarkers for COVID-19." (PMID 35885892, 2022). "Additionally, we found that PCs in patients with severe COVID-19 had higher expression levels of inflammation genes (TNFSF10, S100A9, and S100A8) and chemokine-related genes (CCR2 and ITGB7) than those in patients with mild COVID-19." (PMID 33936072, 2021). "Our data demonstrated strong enrichment of CCL2/19/20, CXCL10, GM-CSF, IL-6/8/15, S100A9, SCGF, TNF and TREM-1 in COVID-19, which could potentially play a critical role on the pathogenesis of the disease." (PMID 34238349, 2021). "Furthermore, blood levels of IL1α, calprotectin (a heterodimer made of S100A8 and S100A9), S100A12, S100B and HGBM1 appear to correlate with COVID-19 severity." (PMID 34293006, 2021). "In brief, the scRNA-seq followed by the immune transcriptomic analysis indicated an activation state (through CD69 and HLA class II genes), chemotaxis (e.g., CCL3 and CCL4), an inflammatory state (e.g., NFKBIA, PIK3R1, S100A9, etc.)in T cells, especially in CD8+T cells, in COVID-19 cases." (PMID 33717140, 2021).
COVID-19 (continued). "In addition, other factors like the immunomodulatory calcium binding protein S100A9 as well as the tissue inhibitor of metalloproteinases-1 (TIMP-1), both of which were described to correlate with poor prognosis in COVID-19 patients, were also significantly decreased by treatment with mFas-Fc." (PMID 38514848, 2024). "Regarding neutrophils, the increased expressions of CD177, IL1R2 and S100A9 in our study agree with the existing literature, which points towards the induction of a dysregulated neutrophil function in COVID-19 patients with increased NET production that aggravates the pathophysiology of COVID-19." (PMID 36389738, 2022). "Cluster 12 and 13 report proteins that are increased in all COVID-19 patients but at higher levels in ICU/F patients which are mainly constituted by proteins playing a role in acute inflammatory response (CRP, ORM1, ORM2, SAA1, SAA2, S100A8, S100A9, Serpin A3)." (PMID 36348270, 2022). "Finally, we demonstrated that influenza virus infection also induces the expression of S100A7, S100A8, S100A9, and S100A12 in the alveolus chip, a finding that is consistent with recent clinical observations from COVID-19 patients that exhibit late stage lung infections with SARS-CoV-2 virus." (PMID 35396513, 2022). "Moreover, SA100A12, together with S100A8 and S100A9, which are also both released by neutrophils, can activate airway epithelial cells to produce MUC5AC, a major mucin protein in the respiratory tract, partly interoperating the excessive mucus discovered in the necropsy of COVID-19 patients." (PMID 34457122, 2021). "In module 2, mono-CD14+ cells in patients with severe COVID-19 exhibited higher expression levels of glycolysis-related genes (LDHA and PKM) and PPP-related genes (PGD and TKT), which may be involved in the proinflammatory response (upregulation of S100A8, S100A9, S100A12, and IL1B)." (PMID 33936072, 2021). "However, it increased expression levels of alarmins S100A12 and S100A9, and it decreased the expression of MHCII and ENTPD1 of CD14+ monocytes, suggesting that persistent levels of SPP1 may contribute to long–COVID-19 pathologies by skewing monocytes toward a proinflammatory phenotype." (PMID 34143756, 2021). "Furthermore, S100A9 amplified the recombinant S2 protein of SARS-CoV-2-induced IL-1β mRNA expression in PBMCs in vitro, suggesting that activation of TLR4 by LPS from the gut microbiota of elderly, diabetic, and hypertensive individuals may be related to the severity of COVID-19." (PMID 34458281, 2021). "In addition, massive release of S100A8/S100A9 calprotectin (a ligand of TLR4 and RAGE) has been observed in plasma from patients with severe rather than mild COVID-19." (PMID 34471261, 2021).
rheumatoid arthritis (58 papers, 2006 to 2025). A chronic, systemic autoimmune disorder characterized by inflammation in the synovial membranes and articular surfaces. "In fact, some of the proteins we identified have also been associated with autoimmune conditions, such as S100A9 and rheumatoid arthritis, CD5L and systemic lupus erythematosus." (PMID 40215752, 2025). "S100A9 levels are raised in autoimmune and pro-inflammatory diseases including rheumatoid arthritis and obesity, which increases the risk of cardiovascular disease." (PMID 36531717, 2022). "Elevated S100A8 and S100A9 protein levels are a hallmark of numerous pathological conditions associated with inflammation (e.g. rheumatoid arthritis, systemic lupus erythematosus, giant cell arteritis, cystic fibrosis, and inflammatory bowel diseases)." (PMID 30870488, 2019). "S100A8 and S100A9 are considered biomarkers of disease activity in chronic inflammatory pathologies associated with impaired matrix remodeling such as rheumatoid arthritis (RA), inflammatory bowel disease (IBD) and cystic fibrosis." (PMID 30728384, 2019). "Calprotectin, a heterodimer of S100A8 and S100A9 subunits, is associated with inflammatory disorders such as rheumatoid arthritis and cystic fibrosis." (PMID 25338166, 2014). "Inflammatory disorders such as chronic bronchitis, cystic fibrosis, and rheumatoid arthritis are also associated with elevated plasma levels of S100A9." (PMID 22457725, 2012). "The calgranulins, specifically S100A8 and S100A9, have been implicated in both rheumatoid arthritis and OA and are considered potent damage-associated molecules which exacerbate inflammation following their release under conditions of cellular stress or injury." (PMID 28173838, 2017). "S100A9 was also used as a marker of inflammation for various diseases, including inflammation bowel disease, rheumatoid arthritis and AD." (PMID 38396791, 2024). "In rheumatoid arthritis, S100A9-mediated neutrophil migration and secretion of pro-inflammatory cytokines from monocytes lead to joint inflammation and joint destruction." (PMID 38448514, 2024). "It is currently known that S100A9 plays a key role in various inflammatory diseases such as tumors and rheumatoid arthritis." (PMID 36635624, 2023). "Calprotectin is a heterodimer formed by two proteins, S100A8 and S100A9, which are the most up-regulated proteins in rheumatoid arthritis." (PMID 37242269, 2023). "S100A8/ S100A9 is the most abundant protein in rheumatoid arthritis synovial fluid (SF) and has a key role in promoting IL-6 expression in fibroblast-like synoviocytes (FLS)." (PMID 36700196, 2022). "S100A8 and S100A9 are the most abundant DAMPs in many inflammatory conditions, like infections, auto-immune diseases, rheumatoid arthritis, or inflammatory bowel disease." (PMID 33643287, 2020). "Elevated concentrations of calprotectin are found in the plasma and synovial fluids of rheumatoid arthritis patients, and S100A9 is known to exacerbate chronic inflammation in models of arthritis." (PMID 31437241, 2019). "Matrix metalloproteinase (MMP) expression in murine and human chondrocytes was directly stimulated by S100A8 and S100A9, thereby promoting the breakdown of cartilage in osteoarthritis and rheumatoid arthritis." (PMID 31781269, 2019). "It has been longer recognized the relationship between the S100A8/S100A9 expression and inflammatory disorders, including rheumatoid arthritis, inflammatory bowel disease, multiple sclerosis." (PMID 30558666, 2018). "Specific peptidic fragments were differentially excreted between groups; fragments of protein S100-A9 and gelsolin were less abundant in rheumatoid arthritis while fragments of uromodulin, complement C3 and fibrinogen were all increasingly excreted." (PMID 25144639, 2014). "S100A9 and A8 are co-expressed mainly by phagocytes in a variety of inflammatory conditions, including rheumatoid arthritis, allograft rejection, inflammatory bowel, and lung diseases." (PMID 22457725, 2012).
rheumatoid arthritis (continued). "Several studies highlighted the role of calprotectin and S100A9 in rheumatoid arthritis (RA) and showed that calprotectin could be a promising biomarker for disease activity." (PMID 33922149, 2021). "S100A8, S100A9, and S100A12 encode proteins that are well-known markers of acute inflammation and previously implicated in several other inflammatory and autoimmune diseases including systemic lupus erythematosus, rheumatoid arthritis, and atherosclerosis." (PMID 32556497, 2020). "In extracellular fluid, increased levels of S100A9/S100A8 etherodimer were reported in numerous inflammation-associated conditions, such as rheumatoid arthritis, Crohn’s Disease, colorectal cancer and in GCF (Gingival Crevicular Fluid) of patients suffering from gingivitis and periodontitis." (PMID 26719749, 2015). "Considering the recently described effect of S100a9 as an inflammation orchestrator in rheumatoid arthritis and lupus erythematosus, it is tempting to speculate that an increased expression of S100a9 could also contribute to the arthropathy process in HH." (PMID 25880808, 2015). "Therefore, S100A9 is a promising potential therapeutic target for inflammatory diseases like rheumatoid arthritis for which alternative therapeutic strategies are needed." (PMID 23029038, 2012). "Protein S100-A9 is highly expressed in the cytoplasm of neutrophils and is found in high levels in extracellular fluids during inflammatory diseases, such as chronic inflammatory bowel disease and rheumatoid arthritis, usually in complex with the related protein S100-A8 (calprotectin)." (PMID 24391738, 2013). "In 2004, Foell and his colleagues found the over-expression of S100 proteins, particularly S100A8, S100A9, and S100A12, at the site of inflammation in Rheumatoid arthritis, chronic inflammatory lung, and bowel disease." (PMID 38956704, 2024). "Serum calprotectin is used as a monitoring and pharmacodynamic biomarker for rheumatoid arthritis, and intriguingly S100A8/S100A9 may have further utility in arthritis as a molecular imaging marker of inflammatory activity." (PMID 33228131, 2020). "Thus, in rheumatoid arthritis patients the amounts of heterodimer were 1000 fold greater as compared to S100A8 and S100A9 homodimers." (PMID 23626736, 2013). "Serum and synovial fluid levels of S100A8, S100A9, and S100A8/A9 were all higher in patients with rheumatoid arthritis (RA) than in patients with osteoarthritis (OA), with the S100A8/A9 heterodimer being prevalent." (PMID 16613612, 2006). "Similarly, in rheumatoid arthritis (RA) and psoriatic arthritis serum concentrations of S100A8/S100A9 are related to the inflammatory activity of arthritis, being superior to other biomarkers such as C-reactive protein and erythrocyte sedimentation rate." (PMID 37372165, 2023). "It is certain that the content of S100A8, S100A9, and S100A12 proteins in serum or fecal are closely related to diseases and can be used as biomarkers for their detection and diagnosis, including rheumatoid arthritis (RA), inflammatory bowel disease (IBD), cancer, etc.." (PMID 38256103, 2024).